TRBV11-3 (T cell receptor beta variable 11-3)
Description:
V region of the variable domain of T cell receptor (TR) beta chain that participates in the antigen recognition. Alpha-beta T cell receptors are antigen specific receptors which are essential to the immune response and are present on the cell surface of T lymphocytes. Recognize peptide-major histocompatibility (MH) (pMH) complexes that are displayed by antigen presenting cells (APC), a prerequisite for efficient T cell adaptive immunity against pathogens. Binding of alpha-beta TR to pMH complex initiates TR-CD3 clustering on the cell surface and intracellular activation of LCK that phosphorylates the ITAM motifs of CD3G, CD3D, CD3E and CD247 enabling the recruitment of ZAP70. In turn ZAP70 phosphorylates LAT, which recruits numerous signaling molecules to form the LAT signalosome. The LAT signalosome propagates signal branching to three major signaling pathways, the calcium, the mitogen-activated protein kinase (MAPK) kinase and the nuclear factor NF-kappa-B (NF-kB) pathways, leading to the mobilization of transcription factors that are critical for gene expression and essential for T cell growth and differentiation. The T cell repertoire is generated in the thymus, by V-(D)-J rearrangement. This repertoire is then shaped by intrathymic selection events to generate a peripheral T cell pool of self-MH restricted, non-autoaggressive T cells. Post-thymic interaction of alpha-beta TR with the pMH complexes shapes TR structural and functional avidity.
Synonyms: TCRBV21S2A2; TRBV113; TCRBV11S3
Tractability: Antibody: UniProt places it where antibodies can reach, with medium confidence; UniProt predicts a signal peptide or a membrane-spanning region; its Gene Ontology location is reachable by antibodies, with medium confidence.
Gene: T-cell receptor variable (V) gene on chromosome 7 (142,554,836 to 142,555,318, forward strand). Ensembl gene ENSG00000276597.
Subcellular location: Cell membrane
Gene Ontology:
Biological process: cell surface receptor signaling pathway
Cellular component: plasma membrane
Homologues: Orthologues: chimpanzee TRBV11-3 (83% identical), mouse Trbv14 (63% identical). Paralogues in human: TRBV11-2 (83% identical), TRBV11-1 (80% identical), TRBV7-2 (61% identical), TRBV7-3 (61% identical), TRBV7-9 (60% identical), TRBV7-6 (58% identical), TRBV12-5 (57% identical), TRBV7-1 (57% identical), TRBV7-4 (57% identical), TRBV7-7 (57% identical), TRBV12-4 (53% identical), TRBV12-3 (52% identical), and 39 more.